ENSG00000252349
Synonyms: LOC124900397
Gene: Small nucleolar RNA gene on chromosome 17 (19,662,000 to 19,662,090, forward strand). Ensembl gene ENSG00000252349.
Gene Ontology:
Biological process: RNA processing
Cellular component: nucleolus
Homologues: Orthologues: mouse Gm55776 (58% identical). Paralogues in human: SNORA31 (85% identical), SNORA31B (68% identical).